PRMT5 (protein arginine methyltransferase 5)
Diseases named in the same sentence as PRMT5 in open-access papers (continued):
Sharing a sentence is not in itself a finding about the gene and the disease.
tumor (continued). "The merged immunofluorescent-staining of MYC and PRMT5 demonstrated a significant co-localization pattern in both HD-MB03 and primary tumor cells." (PMID 31694585, 2019). "PRMT5 regulates this pathway through direct methylation of histones H3R8 and H4R3 in the promoter region of RB1, RBL1 and RBL2 tumor suppressor genes." (PMID 30613353, 2018). "Collectively, these observations indicate FOXP1 is oncogenic, and that epigenetic regulation of the FOXP1 promoter is one mechanism by which PRMT5 drives BCSC function, promoting tumour initiation and drug resistance." (PMID 29876520, 2018). "Mechanistically, PRMT5 enhances NF-kB activation by targeting crucial anti-apoptotic genes such as BCLXL and c-IAP1, thereby inhibiting tumor cell apoptosis and sustaining proliferation." (PMID 30713476, 2018). "To investigate PRMT5 expression in HCC, we performed immunohistochemical staining on tumor tissue microarrays (TMAs) containing pairs of HCC specimens and corresponding pericancerous liver tissues from an HCC cohort (n = 138)." (PMID 29441724, 2018). "PRMT5 expression was evaluable in 209 tumors and it was predominately cytoplasmic in the OPSCC tumor samples (72.2%; 151/209)." (PMID 28107179, 2017). "In order to determine the effects of PRMT5 depletion on BCSC and tumor biology, mice in each group were aged and sacrificed when control animals reached license limit." (PMID 29262329, 2017). "For example, acting as a tumor suppressor, E2F1 methylated by PRMT5 can increase tumor cell growth and inhibit apoptosis." (PMID 27708221, 2016). "Here, we provide considerable evidence of a positive role for PRMT5 and CDK4 in tumor cell cycle regulation." (PMID 27708221, 2016). "In the high glucose condition, PRMT5 was shown to emphatically interact with CDK4, releasing it from CDKN2A and leading the CDK4-RB-E2F axis to an active state for tumor growth." (PMID 27708221, 2016). "Inhibition of PRMT5 by AMI-1 or knockdown of PRMT5 by siRNA in CRC led to the restoration of critical regulatory pathways affecting cell growth, survival, migration and tumor suppressor activity." (PMID 26078354, 2015). "Further, our results suggest that CRN5 affects tumour-related cell functions on several levels, directly on the actin cytoskeleton and more indirectly via modulation of the MAPK14 and PRMT5 signalling pathways." (PMID 26373535, 2015). "This function of PRMT5 complements the earlier demonstration that PRMT5 methylates H3R8 and H4R3 at specific target loci, including repressed tumour suppressor genes." (PMID 24097435, 2014). "While PRMT5 overexpression and its cellular localization appear to be associated with more aggressive tumor phenotypes, alterations in PRMT5 expression alone may not necessarily lead to malignant transformation per se, but reflect changes of epigenetic control in oncogenesis." (PMID 24326178, 2013). "Knockdown of PRMT5 was shown to sensitize tumor cells to TRAIL-induced cell death, while PRMT5 overexpression conferred TRAIL resistance." (PMID 21756247, 2011). "Notably, combined treatment with the PRMT5 inhibitor GSK3326595 and DMF synergistically enhances anti-tumor activity in a patient-derived xenograft (PDX) model." (PMID 41998301, 2026). "In this section, we will explore the different therapeutic targets identified over time, beginning with the recently discovered PRMT5/methionine adenosyltransferase 2A (MAT2A) axis and then tracing back to earlier targets that have shaped our understanding of MTAP-deleted tumor vulnerabilities." (PMID 41439984, 2025). "To clarify whether PRMT5 directly regulates the CXCL10/CXCR3 signaling pathway, we established tumor models in CXCR3 KO mice with control cells and PRMT5 knockdown U14 cells." (PMID 41463372, 2025). "PRMT5-mediated methylation of MST2 inhibits the Hippo signaling pathway, promoting PDAC progression and metastasis, while PRMT5 inhibition restores Hippo pathway activity and suppresses tumor growth." (PMID 40707469, 2025).
tumor (continued). "In the present study, a novel mechanism was revealed whereby PRMT5 inhibition promotes CPT‐11 sensitivity and synergistically induces a dMMR‐like state in MSS CRC, further activating the cGAS‐STING signaling pathway and boosting anti‐tumor immunity." (PMID 40344511, 2025). "Finally, we used the GEPIA database to determine which of the remaining proteins have an expressional correlation with PRMT5 and KRAS in CRC patient tumor samples." (PMID 40864819, 2025). "Although MTA-cooperative PRMT5 inhibitors have shown extensive potential in multiple MTAP-null preclinical models, questions have been raised about the presumed accumulation of MTA in the presence of the tumor microenvironment." (PMID 41439984, 2025). "We observed a PRMT5-dependent induction of EMT and tumor cell invasion under hypoxia." (PMID 41150697, 2025). "Moreover, dual targeting of PRMT5 and the PI3K/mTOR or MEK/ERK pathways enhances anti-tumor efficacy, supporting the development of biomarker-guided combination strategies to improve therapeutic outcomes in CRC." (PMID 41226455, 2025). "PRMT5 catalyzes the formation of symmetric dimethylation (SDMA) by transferring 1 or 2 methyl groups from S-adenosylmethionine to the guanidino nitrogen of protein arginine, thereby influencing tumor progression through multiple pathways." (PMID 40756764, 2025). "Despite promising anti-tumor activity in vitro, the clinical efficacy of PRMT5 inhibitors is often limited by the tumor microenvironment, particularly the impact of non-malignant cells that attenuate drug activity." (PMID 42021873, 2025). "Silencing of PRMT5 leads to reduced MYCN levels and impaired tumor cell growth, suggesting that PRMT5 inhibitors could serve as potential therapeutic agents for MYC/MYCN-driven MB." (PMID 40365336, 2025). "Consistent with reported studies, PRMT5 knockdown or inhibition induced anti‐PAAD subtypes including suppressed colony formation, suppressed proliferation, increased apoptosis process, and prolonged survival of tumor‐bearing mouse." (PMID 40384988, 2025). "The studies approved that PRMT5 could orchestrate EGFR and AKT networks to promote EMT in the tumor cells." (PMID 39994841, 2025). "In malignant melanoma, PRMT5 suppresses the transcription of NLRC5, a key transactivator of MHC-I genes, thereby downregulating the expression of genes involved in antigen processing and presentation and impairing tumor immunogenicity." (PMID 41204384, 2025). "We have previously shown that BCSCs express higher levels of PRMT5 compared to bulk MCF7 cells and ectopic overexpression of PRMT5 and its essential cofactor MEP50 significantly increases BCSC frequency, self-renewal, and tumour initiation in vivo." (PMID 39695328, 2025). "Finally, we showed that a specific PRMT5 inhibitor, EPZ015666, effectively suppresses tumor growth in vivo." (PMID 41463372, 2025). "Similarly, hnRNPA1 is methylated by PRMT3, PRMT4, PRMT5, and PRMT7, with methylation affecting alternative splicing patterns relevant to tumor progression and therapy resistance." (PMID 41204384, 2025). "Thus, overexpression of PRMT5 in PDAC cells facilitates tumor EMT, thereby promoting tumor invasion and metastasis." (PMID 38612768, 2024). "In addition, as was observed for the siRNA targeting of PRMT5, LLY-283 treatment also induced the enhancement of tumor cell radiosensitivity." (PMID 39068290, 2024). "Moreover, both tumor suppressor genes have other SL partners, including VEGFA and PRMT5, defining a dysfunctional network with multiple vulnerabilities that confer treatment opportunities for network takedown." (PMID 38187871, 2024). "The interplay mechanism between IDH, O-6-methylguanine-DNA methyltransferase (MGMT)-promoter methylation, and protein methyltransferase proteins-5 (PRMT5) activity, with tumor progression has never been described." (PMID 38827324, 2024). "Increased levels of PRMT5 and FUBP1 were detected in tumor tissues compared with adjacent tissues." (PMID 39146021, 2024).
tumor (continued). "Mechanistically, we find that PRMT5 symmetrically dimethylates alpha‐enolase (ENO1) at arginine 9 to promotes active ENO1 dimer formation, which increases glycolysis flux and accelerates tumor growth." (PMID 36999124, 2023). "PRMT5 was first characterized as a transcriptional repressor by catalyzing the symmetric dimethylation of histone H3 arginine 8 (H3R8) and H4 arginine 3 (H4R3), leading to transcriptional repression of tumor-suppressor genes." (PMID 37173967, 2023). "Here we have reviewed current pharmacological methods of targeting SAM production via MAT2A inhibition and direct PRMT5 inhibition (both of which reduce PRMT5-specific methylation reactions) and reported evidence for and against the selectivity of these treatments for MTAP-negative tumours." (PMID 37795443, 2023). "In this study, PRMT1, PRMT2, PRMT5, and PRMT8 were significantly highly expressed in After Tumor." (PMID 38136558, 2023). "All Eμ-PRMT5/TCL1 mice between ages 6–15 months became visibly ill and developed a neoplasia with a similar CLL-like immunophenotype to Eμ-TCL1 mice; although Eμ-PRMT5/TCL1 mice frequently presented with large cells circulating in the blood (FSChigh), a rare event in Eμ-TCL1 mice." (PMID 36609611, 2023). "MTAP loss in MTAP-expressing tumor cells results in increased sensitivity to PRMT5 inhibition, while MTAP re-expression in MTAP-deleted tumor cells could rescue PRMT5 reliance." (PMID 37091983, 2023). "PRMT5 demonstrated predominantly nuclear localization in both HD-MB03 and primary tumor cells." (PMID 38136401, 2023). "It has been demonstrated that the growth of MTAP-lacked tumor cells is abrogated by PRMT5 inhibition, making PRMT5 a synthetic lethal target for MTAP-lacked tumors." (PMID 37091983, 2023). "Notably, PRMT1, PRMT2, PRMT3, and PRMT7 exhibited upregulation, while PRMT5, PRMT6, and PRMT8 displayed downregulation in tumor." (PMID 37781030, 2023). "Tumor 1 was representative of tumors not expressing nuclear PRMT5 and displayed no ERα/SDMA methylation, whereas Tumor 2 was representative of tumors with high nuclear PRMT5 staining and had a high nuclear ERα/SDMA expression." (PMID 37458145, 2023). "Furthermore, inhibition of KLF5 by mifepristone and its derivatives 22-24, metformin 25, mithramycin A 26, super-enhancer inhibitors 27, and the protein arginine N-methyltransferase 5 (PRMT5) inhibitor, PJ-68 28, suppress BLBC stemness and tumor growth." (PMID 35342356, 2022). "Akt activation upregulates SREBP1 gene expression, and it also inhibits the ubiquitin-proteasome pathway degradation of SREBP1 through protein arginine methyltransferase 5 (PRMT5), inducing SREBP1 hyperactivity, which results in de novo lipogenesis and tumor growth." (PMID 36613455, 2022). "We show that PRMT5 modulates AKT1 activation via direct methylation of Arg 15 and that AKT signaling regulates the expression of essential EMT-TFs that orchestrate the EMT program responsible for tumor metastasis." (PMID 35803962, 2022). "Indeed, PRMT5 and type I PRMT inhibition suppressed sDMA and aDMA functions in RNA-binding proteins involved in splicing regulation, leading to tumor-suppression responses in animal leukemia models with splicing factor mutations." (PMID 35493527, 2022). "Combination therapy demonstrated activity in vivo, since MSI2 depletion resulted in a 50% reduction of tumor growth which was further reduced with the addition of PRMT5 inhibitor (80% drop) without inducing toxicity." (PMID 36167829, 2022).
tumor (continued). "Which of the many functions ascribed to PRMT5 that contributes to its tumor-promoting functions is not fully understood." (PMID 35602594, 2022). "EPZ015666, the PRMT5 inhibitor, could reduce the SDMA modification and inhibition of tumor growth of 143B and HOS/MNNG." (PMID 35875497, 2022). "Furthermore, PRMT5, EZH2 and CDKN2B protein expression levels in CRC samples (80 tumor and 80 normal tissues) were analyzed by IHC staining." (PMID 33664859, 2021). "Since PRMT5 depletion reduced expression of STAT3 target genes, we analyzed the status of STAT3 tyrosine phosphorylation at Y705 (p‐STAT3) in mouse tumor samples." (PMID 34026434, 2021). "Protein arginine methyltransferase 5 (PRMT5), a histone methyltransferase responsible for the symmetric dimethylation of histone H4 on Arg 3 (H4R3me2s), is an enzyme that participates in tumor cell progression in a variety of hematological malignancies." (PMID 34531375, 2021). "Furthermore, we observed that increased PRMT5 expression predicted unfavourable patient survival in CRC patients and in the subgroup of patients with a tumour size of ≤5 cm." (PMID 33675123, 2021). "PRMT5 activity suppresses anti-tumor immune responses by supporting tumor intrinsic mechanisms allowing immune evasion, Treg function, and repression of IFN-1 and MHCI pathways, providing a rationale for combining PRMT5 inhibitors with ICT." (PMID 32743345, 2020). "Several non-histone proteins with tumor promoting or suppressing functions have been identified as PRMT5 substrates." (PMID 32743345, 2020). "Notably, combined treatment with type I PRMT inhibitors (GSK3368715 or MS023) and PRMT5 inhibitors (GSK3326595 or GSK3203591) slows in vitro and in vivo growth of tumor cells more effectively than treatment with either alone." (PMID 32743345, 2020). "LKB1, a kinase with tumor suppressor function, phosphorylates multiple threonines (T132, 139 and 144) in the PRMT5 TIM-barrel domains required for MEP50, pICln and RIOK1 interaction, suppressing PRMT5 enzymatic activity." (PMID 32743345, 2020). "Finally, through subcutaneous injection of PRMT5-silenced SW1990 cells into nude mice, we demonstrated that silencing PRMT5 decreased the tumor formation capacity of cells compared with that of the corresponding Scr cells." (PMID 30922330, 2019). "PRMT5-catalyzed histone H3 arginine 8 (R8) and H4R3 symmetric dimethylation has been shown to repress expression of several tumor suppressor genes such as Suppressor of Tumorigenicity 7 (ST7), retinoblastoma (RB) family of tumor suppressors, and Protein Tyrosine Phosphatase Receptor-type O (PTPROt)." (PMID 30613353, 2018). "In this study we have provided new insights into the regulation of tumor suppressor pathways demonstrating that MP is a negative regulator of the PRMT5 oncoprotein." (PMID 28074910, 2017). "Using a systematic in vitro and in vivo approach to analyze the contribution of PRMT5 to BCSC function, we found that PRMT5 depletion in established estrogen receptor (ER)+ xenografts not only reduced tumor growth but substantially reduced the proportion of BCSCs after serial transplantation." (PMID 29262329, 2017).
tumor (continued). "Furthermore, the CDK4 mutant R24A weakly binds to PRMT5, inhibiting HCC cell cycle progression and tumor growth." (PMID 27708221, 2016). "Protein arginine methyltransferase 5 (PRMT5), a Type II arginine methyltransferase, which has been reported to be involved in the regulation of multiple tumorigenesis pathways, usually can only be stained by immunohistostaining on tumor biopsy." (PMID 27878106, 2016). "In conclusion, the interaction between PRMT5 and CDK4 rendered a tumor-promoting effect." (PMID 27708221, 2016). "In the present study, we demonstrate that the expression level of CRN5 is associated with the malignant progression of colon carcinoma, and that CRN5 over-expression led to elevated tumour cell migration velocity as well as altered MAPK14 and PRMT5 signalling pathways." (PMID 26373535, 2015). "Importantly, this unbiased screening identified several hits that positively regulate PRMT5 expression, including oncoproteins such as HRAS and BRAF, whereas tumor suppressors like KEAP1 were identified as top-scoring hits that negatively regulate PMRT5 levels." (PMID 40091834, 2025). "All in, PRMT5 interacts with CD38 activating the phosphorylation of GSK3β through the ADO-cAMP-PKA axis, augmenting stabilization of PD-L1 expression and subsequently inhibiting CD8+ T cell-mediated tumor cell killing, supporting tumor cells to evade immune surveillance." (PMID 40701777, 2025). "We found that PRMT5 inhibition in combination with the DNA‐damaging chemotherapeutic drug CPT‐11 induced a dMMR‐like state, thereby enhancing cGAS‐STING pathway activation and anti‐tumor immune reprogramming, ultimately increasing the sensitivity to ICIs treatment in MSS CRC." (PMID 40344511, 2025). "Similarly, ADC tumor samples exhibited a 1.94-fold decrease (p = 0.0145), indicating a consistent downregulation of pRb expression in tumors, likely reflecting the downstream impact of the dysregulated PPM1B/MP/PRMT5/H2A pathway." (PMID 41301499, 2025). "Furthermore, PRMT5 inhibitors are particularly effective in MTAP-deleted intrahepatic cholangiocarcinoma, where they enhance the efficacy of cisplatin and gemcitabine and suppress the growth of tumor organoids." (PMID 41204384, 2025). "Concurrently, PRMT5-mediated methylation of ULK1 at R170 promotes T180 phosphorylation, activating autophagy via ATG13 and Beclin1 phosphorylation, which enhances mitochondrial clearance, reduces oxygen consumption, and supports tumor survival and proliferation." (PMID 41204384, 2025). "Combining PRMT5 inhibitors with DNA-damaging chemotherapies and/or innovative DDR inhibitors targeting could widen the therapeutic window that promotes effective BCSC and bulk tumour cell eradication whilst minimising unwanted toxicities." (PMID 39695328, 2025). "Furthermore, initial xenograft models suggest that first-generation PRMT5 inhibitors effective in MTAP-competent genetic backgrounds are cytostatic rather than cytotoxic because tumours regrew after treatment withdrawal." (PMID 39695328, 2025). "Thus, in addition to reducing DMG cell growth, PRMT5 inhibition reduced DMG stem-like activity post treatment, which could be a beneficial effect to help prevent tumour re-initiation post treatment." (PMID 38172189, 2024). "The underlying mechanism is by MTDIA causing accumulation of MTA in tissues regardless of tumor MTAP genotype due to the loss of MTA catabolism in all cells, thereby enhancing the MTA:SAM ratio, inhibiting PRMT5 activity, and providing dose-dependent sensitivity to MAT2a inhibitors." (PMID 38000655, 2024). "Importantly, PRMT5 methylates vCyclin symmetrically and stabilizes vCyclin in a methyltransferase activity-dependent manner, thereby promoting cell cycle progression and proliferation of KSHV latently infected tumor cells." (PMID 39255317, 2024).